TGFB1 (transforming growth factor beta 1)
Diseases named in the same sentence as TGFB1 in open-access papers (continued):
Sharing a sentence is not in itself a finding about the gene and the disease.
colitis (377 papers, 2006 to 2026). Inflammation of the colon. "In dextran sodium sulfate-induced colitis models, it was determined that the use of EO caused a significant decrease in the expression levels of TGFB1 and CASP3 in colon tissue and alleviated inflammation." (PMID 40233022, 2025). "L. acidophilus blocks the colitis-associated immune response of the IL-23/Th17 axis by downregulating the activity of IL-17, TNFα, IL-23, TGFβ1, and STAT336." (PMID 32123288, 2020). "In addition, it has been proven that mice with selective deletion of TGFβ1 signaling in gut epithelium are more susceptible either to colitis induced by dextran sodium sulphate or to invasive intestinal tumors." (PMID 33810512, 2021). "Pirfenidone effectively reduced the deposition of collagen in colitis-associated fibrosis and significantly suppressed the mRNA expression of COL1A2, COL3A1, and TGFB1." (PMID 39684719, 2024). "And TGFB1 knockdown significantly impaired the ability of hUC-MSCs to induce Treg cells and treat colitis." (PMID 38956621, 2024). "Knockdown of TGFB1 in hUC-MSCs resulted in a noticeable reduction of Treg cells in MLNs and the eventually failure of hUC-MSCs therapy in colitis." (PMID 38956621, 2024). "GA administration in rats with dextran sodium sulfate-induced colitis resulted in a reduction in the severity of colitis, colonic fibrosis, and TGFβ1 expression." (PMID 36671523, 2023). "In the TNBS colitis prevention trial, Hif1a and Tgfb1 expression was elevated by MTADV as in the therapeutic trial, but it also caused an increase in Tnfa, Vegfa, and Il10." (PMID 37047397, 2023). "Studies have demonstrated that captopril is effective in preventing colonic fibrosis in TNBS-induced colitis due to the blockade of TGFβ-1 overexpression and a direct down-regulation of TGFβ-1 transcript." (PMID 35900609, 2022). "COX2 byproduct prostaglandin-E2 (PGE2) and TGFβ1 are known to activate oncogenic β-catenin signaling and NF-κB signaling, respectively and both have been independently implicated in CAC and colitis development." (PMID 36584137, 2022). "BMSC transplantation in a DSS-induced colitis mice model appears to be a promising therapy to recruit macrophages and to produce TGFβ1 resulting in alleviation of colonic pathology." (PMID 33287220, 2020). "In fact, through the use of T cell-specific Tgfb1 deletion and subsequent Treg cotransfer experiments in Rag1−/− mice, the inhibition of Th1 differentiation and colitis was shown to be dependent upon TGF-β1 production by Tregs." (PMID 29706961, 2018). "In this study, we showed for the first time that L. acidophilus inhibits the colitis-mediated increase in TGFβ1 and IL-23 expression in mouse colon." (PMID 25973440, 2015). "In another colitis model induced with oral dextran sulfate, EO given by gavage for 11 days alleviated the clinical findings in mice and significantly decreased the gene expression levels of IL-1β, TGFβ1 and IL-6 in colon tissue." (PMID 40233022, 2025). "In the preventive trial with DSS-colitis, dexamethasone-induced an increase in Hif1a and Il6, and a decrease in Tjp1 expression compared to controls, while Tgfb1 and Vegfa expression was increased in the MTADV group, as well as Nos2 and Tjp1 in comparison to dexamethasone." (PMID 37047397, 2023). "Additionally, COX2 and TGFβ1 are known to activate oncogenic β-catenin signaling and NF-κB signaling, respectively and have been implicated in colitis and CAC colitis development." (PMID 36584137, 2022). "Interestingly, accumulation of pro-inflammatory factors such as cyclooxygenase (COX-1 and 2) and TGFβ1 (transforming growth factor beta-1) in the GI-tract have been reported after heavy-ion exposure, as well as during colitis and CAC development." (PMID 36584137, 2022). "Notably, higher expression of TGFβ1, iNOS, and COX2 (Ptges) is also associated with colitis and CAC incidence." (PMID 36584137, 2022). "In contrast, PAMK treatment slightly increased the expression of Tgfb1 and Il10 in colitis mice." (PMID 36341374, 2022).
colitis (continued). "A previous study highlighted the protective effects of intraperitoneally administered pentoxifylline—a xanthine alkaloid derived from the seeds of the cacao tree (Theobroma cacao)—on TNBS colitis in rats through limiting TGFβ1 accumulation and MMP3 and MMP9 activation." (PMID 32855621, 2020). "Mice with selective deletion of TGFβ1 signaling in the intestinal epithelium do not develop inflammation but are more susceptible to DSS-colitis." (PMID 29973939, 2018). "Thus, conditional deletion of TGFβ1 expression in CD4+ and CD8+ T-cells (by crossing mice carrying a conditional floxed allele of TGFβ1 with mice expressing CD4-Cre) resulted in age-related autoimmune disease, characterised by T-cell activation and colitis." (PMID 22902140, 2012). "Surprisingly, Tgfb1, Il17ra, Il23a, Il6ra, Ror1, Tnf, Tgfbr2, Ccr2, and Il17c were downregulated by cigarette smoke exposure in TNBS-induced colitis Gpr15−/− mice compared with similarly treated Gpr15+/+ mice." (PMID 40957881, 2025). "In a study investigating the effect of orally administered 25% HTyr containing olive leaf extract on rats with the acetic acid-induced colitis model, it was shown that HTyr inhibited OS and inflammation by reducing colonic MDA and TGFB1 expression." (PMID 40233022, 2025). "In a pre-clinical study, RXC008 demonstrated anti-fibrotic effects in adoptive T-cell transfer and chronic DSS murine models of colitis, suppressing fibrosis and reducing the expression of fibrotic markers such as COL1A1, COL1A2, and TGFB1." (PMID 39684719, 2024). "Regarding the DSS-colitis therapeutic design, BLI showed a moderate positive correlation with Il6, while Tgfb1 and the Il10/Il1b1, Il10/Il6, Tgfb1/Il1b1, Tgfb1/Il6, and Tgfb1/Tnfa ratios correlated in the opposite way." (PMID 37047397, 2023). "Furthermore, the mRNA level of TGFB1 was up-regulated much higher than that of TGFB2 and TGFB3 in hUC-MSCs stimulated by MLNs homogenates from colitis mice." (PMID 38956621, 2024). "There is also prominent participation of Il10 and Tgfb1 in the immune networks of TNBS-colitis regardless of the trial and sex that counteracts the inflammatory imbalance." (PMID 37047397, 2023). "Anti-MCH antibody suppressed the production of fibrotic genes in experimental colitis, and oral administration of MCHR1 antagonist decreased Col1α1 and TGFβ1 expression levels in a dose-dependent manner in the liver of C57BL/6 J mice with severe hepatic steatosis." (PMID 34912333, 2021). "However, when using transcriptomics, it was observed that Tgfb1 mRNA levels were lower in the non-inflamed P62 group, as well as in DSS-pExu and DSS-P62 groups, when compared to the colitis DSS group (p < 0.05)." (PMID 38680913, 2024).
Hyperglycemia (339 papers, 2007 to 2026). An increased concentration of glucose in the blood. "Our data agree with previous observations that the role of increased lactate levels and PFK activity, which are seen in hyperglycemia, is associated with immunometabolic regulation of TGFβ1 expression and perhaps that of other immunoregulatory molecules." (PMID 39062148, 2024). "This study further identified the reduction of renal tubular PNPT1 induced by TGFβ1, hyperglycemia or LPS as the mechanism underlying the relocation of mt-dsRNAs from mitochondria into the cytoplasm." (PMID 36869030, 2023). "Rat islets (300 per mouse) transduced with an AAV2/5 vector harboring the immunosuppressive transgene, tgfβ1, retain the ability to correct hyperglycemia when transplanted into immune-deficient diabetic mice." (PMID 19450275, 2009). "The activation of the latent form of TGFβ1 may be facilitated by commonly hyperglycemia-associated conditions, including metabolic acidosis, oxidative stress, and the increased expression of thrombospondin-1, integrins, or plasmin." (PMID 36430743, 2022). "Yan and colleagues showed that hypothalamic injection of TGF-β1 caused hyperglycemia and glucose intolerance in mice, conversely, the TGFβ-1 deficient mice (Tgfb1+/−) were protected from hypothalamic inflammation and type 2 diabetes induced by high-fat diet (HFD)." (PMID 28854149, 2017). "The characteristic increase in IL-6 during COVID-19 inhibits BMPR2, which normally protects against increased TGFβ signaling, and upregulated TGFβ1 contributes to hyperglycemia." (PMID 38674024, 2024). "Hyperglycaemia is thought to upregulate the expression of profibrotic factors such as transforming growth factor beta 1 and down-regulate the activity of the matrix metalloproteinases." (PMID 38443793, 2024). "Taken together, this review proposes a wider comprehensive aspect of molecular mechanism explaining interrelated hypothetical pathways of TGFβ-1, hyperglycemia, and miRNA." (PMID 37306727, 2023). "Recently, the biomolecular mechanism of cardiac fibrosis in the hyperglycemia setting has been focusing around transforming growth factor β-1 (TGFβ-1) as a major factor." (PMID 37306727, 2023). "Meg3 overexpression inhibits TGFB1-stimulated cell proliferation and apoptosis, while hyperglycaemia stimulates TGFB1 expression." (PMID 38288471, 2023). "The only difference between the TGFβ1/SAL and TGFβ1 TG/STZ groups was the presence of hyperglycemia with high circulating levels of active TGFβ1." (PMID 36430743, 2022). "The effects of TGFβ1 on endothelial cells seem to be concentration-dependent and can be enhanced or inhibited in the presence of other regulators, and hyperglycemia increases its activity." (PMID 34930438, 2021). "They found out that Bcl2-modifying factor (Bmf), a pro-apoptotic protein is induced by hyperglycemia via ROS and growth factor (TGFβ1) and upregulated in diabetic kidneys of rats and humans." (PMID 33562428, 2021). "Previously, many pathways were found to involve hyperglycaemia related to the proliferation and metastasis of cancer cells, such as the TGFβ1/PI3K/AKT signalling pathway and microRNA (miRNA)-associated pathways." (PMID 29340090, 2017). "Our current study showed that TSP1-mediated TGFβ1/Smads signaling is intensively involved in macrovascular fibrosis induced by hyperglycemia." (PMID 25884585, 2015). "Experimental and clinical studies indicate that hyperglycemia stimulates the production of TGFβ1, thrombospondin 1 (TSP1), and angiotensin II (Ang II) in the diabetic condition." (PMID 25884585, 2015). "When PTEN undergoes polyubiquitination at lysine 80 through MEX3C-mediated K27 linkage, it exhibits a pro-inflammatory effect by promoting the secretion of interleukin-6 (IL-6) and transforming growth factor-beta 1 (TGF-β), thereby exacerbating hyperglycemia-induced EMT." (PMID 39165377, 2024).
Hyperglycemia (continued). "Because hyperglycemia activates the TGFβ response and we demonstrated that Set7KO regulates key renal cell clusters, we stimulated human podocytes, glomerular endothelial cells, macrophage monocytes, and proximal tubular cells with PFI-2 before high-glucose and TGFβ1 stimulation." (PMID 38630537, 2024). "Several studies have found that LPS or other factors, such as polymeric immunoglobulin A1 (pIgA1) and hyperglycemia, can activate mesangial cells to produce pro-inflammatory cytokines, including IL-6, transforming growth factor-beta 1 (TGF-beta 1), TNF-α and NO." (PMID 37488573, 2023). "Although the underlying molecular basis remains unknown, mechanistical studies indicate that PNPT1 reduction in renal tubular cells can be achieved by renal tubular cell injury factors TGFβ1, hyperglycemia and LPS." (PMID 36869030, 2023). "In addition to enhancing the production of TGFβ1, hyperglycemia can also promote the inflammatory response by activating the macrophages through the TGFβ1-activated kinase (TAK1) that induces the release of pro-inflammatory cytokines by NFκB activation." (PMID 36430743, 2022). "An important factor that triggers the enhanced expression of TGFβ1 in the kidneys is hyperglycemia." (PMID 36430743, 2022). "A critical question that needs to be addressed is: to what extent can renal dysfunction be attributed to the direct effect of hyperglycemia on the diabetic TGFβ1 TG mice due to insulin resistance (and the related glucotoxicity) compared to the increased circulating active TGFβ1 levels?" (PMID 36430743, 2022). "In the present study, we induced a DM state in WT mice and TGFβ1 TG mice overexpressing the human TGFβ1 in the kidneys and evaluated whether hyperglycemia affected the circulating levels of TGFβ1." (PMID 36430743, 2022). "Previous studies have shown that the activation of the transforming growth factor-beta 1 (TGF-β1)/micro-RNA 200b (miR-200b)/VEGF pathway by hyperglycemia might play an essential role in the destruction of the blood–retinal barrier (BRB) and in the pathogenesis of DR." (PMID 40385359, 2025). "One of the more important findings of this work was that PVT1 effects on expression of FN1, COL4A1, and PAI-1 may be mediated independently of TGFB1, a well-known profibrotic factor which promotes tissue fibrosis by upregulating genes encoding ECM proteins in response to hyperglycemia." (PMID 21526116, 2011). "First of all, we analyzed mRNA levels of EMT and CSC inducers—namely, the cytokines IL-6, IL-8, TNF-α and TGFβ-1—in PDEC exposed to M1-polarized macrophages and/or hyperglycemia." (PMID 34064969, 2021). "TSP1-mediated TGFβ1/Smads signaling is activated and contributes to the redundant accumulation of ECM induced by hyperglycemia in the rat diabetic thoracic aorta." (PMID 25884585, 2015). "The strong expressions of proliferation markers Ki67 and TGFβ1 further supported that CoPP treatment could promote ARPE-19 cell proliferation under both normoglycemia and hyperglycemia." (PMID 39857426, 2025). "We demonstrated that PTβR2I binds with TβR2 and differentially regulates TGFβ1 pathways: PTβR2I downregulates the TGFβ1/p38 pathway while not affecting the TGFβ1/Smad-2/3 pathway under the hyperglycemia environment in diabetic wounds." (PMID 37422462, 2023). "This increment can be considered an effect of glucotoxicity, rather than hyperglycaemia‐induced hyperosmolarity, since the TGFB1 level was not increased by the isosmotic control mannitol treatment." (PMID 30324679, 2019). "Furthermore, we found that Flu significantly decreased the expression of STAT1 and TGFβ1 in HK-2 cells, which indicates a possible mechanism that DAPA ameliorates EMT by suppressing hyperglycemia-induced STAT1/TGFβ1 pathway." (PMID 31333586, 2019).
Hyperglycemia (continued). "Our study revealed that DAPA successfully inhibited hyperglycaemia-induced ECM deposition in the kidneys of diabetic mice, attenuated EMT of tubular epithelial cells under hyperglycemic conditions, and suppressed the level of the profibrotic factors STAT1 and TGFβ1 both in vivo and in vitro." (PMID 31333586, 2019). "Therefore, we speculate that the explanation for the significant and rapid progression of renal dysfunction in the TGFβ1 TG/STZ group compared to the TGFβ1 TG/SAL group and diabetic WT mice is the presence of hyperglycemia with a high circulating level of active TGFβ1." (PMID 36430743, 2022). "Finally, mRNA levels of TGFβ-1 were almost not affected in H6c7-pBp cells and slightly enhanced after coculture with macrophages predominantly in H6c7-kras cells after short-term culture, while hyperglycemia had not effect." (PMID 34064969, 2021). "We found that the blood levels of active TGFβ1 were significantly increased in the diabetic TGFβ1 TG (TGFβ1 TG/STZ) compared to the non-diabetic TGFβ1 TG (TGFβ1 TG/SAL) mice and diabetic WT mice (WT/STZ), suggesting an enhanced TGFβ1 activation in the presence of hyperglycemia." (PMID 36430743, 2022).
Obesity (330 papers, 2008 to 2026). Accumulation of substantial excess body fat. "Atrial fibrillation (AF), characterized by structural remodeling involving atrial myocardial degradation and fibrosis, is linked with obesity and transforming growth factor beta 1 (TGF-β1)." (PMID 38396862, 2024). "Significant associations have been found between TGFβ1 levels and hepatic abnormalities such as steatosis, obesity, and CRP." (PMID 37626717, 2023). "Tgfb1, a pleiotropic cytokine, regulates the growth and differentiation of various cell types and is associated with insulin resistance, obesity, and hepatic steatosis." (PMID 36426356, 2022). "Transforming growth factor beta 1 (TGFβ1) is associated with obesity and insulin resistance in both animal and human models." (PMID 36548206, 2022). "TGFβ1 methylation was decreased in the saliva of pregnant women who were obese in comparison to non-pregnant controls with normal BMI, suggesting an upregulation of TGFβ1 associated with obesity and gestation." (PMID 37626717, 2023). "This discrepancy suggests that TGFβ1 may control microglia through multiple pathways, some of which are more susceptible to impairment with obesity, and also warrants continued investigation into SAMe’s ability to modulate TGFβ1." (PMID 33917279, 2021). "However, TGFβ1 has been associated with obesity and weight gain in adults." (PMID 37626717, 2023). "While TGFB1 inhibits ASPC commitment to adipocytes, CDK5 has been associated with dysregulated PPARγ signaling in obesity." (PMID 40975767, 2025). "Among the obesity groups, significant differences in Ccl2 and Tgfb1 expression were found between the HFD-30:1 and HFD-5:1 groups." (PMID 40573106, 2025). "Many genes on this list are involved in different processes associated with T2DM development, such as obesity (SREBF1 and H6PD), inflammation (TGFB1), and insulin resistance (RPTOR and AKT1)." (PMID 39273245, 2024). "After adjusting for obesity, comorbidities, age, smoking, alcohol consumption, and ethnicity, our model predicted 66% and 48% increases of TGFβ1 and TGFβ2 by T2D, respectively, in this cohort of AA and LA." (PMID 38541912, 2024). "These are produced in macrophages and other lymphoid cells, and their levels, particularly TGFβ1, rise in obese adipose tissue in mouse models as well as in plasma in human obesity." (PMID 36038791, 2022). "Evidence also shows that the inhibition of the TGFβ1/SMAD pathway protects the body against diet-induced obesity and DM and that the TGFβ1 level is significantly correlated with adipose deposition in experimental animals and human subjects." (PMID 36430743, 2022). "Based on its relevance in obesity-associated inflammation and colon carcinogenesis, the VAT was selected to study MFAP2 and TGFB1 gene expression levels." (PMID 34445187, 2021). "In the case of IBS with prevailing diarrhea, especially its comorbid course with obesity, cytokine imbalance was observed, which was manifested by a decreased amount of IL-10 in the blood serum and increased levels of TNFα and TGFβ1." (PMID 34621378, 2021). "It is very likely that circulating levels of TGFβ1 are elevated in animals with obesity and activates the TGFβ signaling pathway in the heart." (PMID 29884823, 2018). "We observed a decrease in homeostatic TGFβ1 production by skin γδ T cells and an inability to upregulate TGFβ1 following injury in obesity and metabolic disease." (PMID 20625397, 2010). "TGF-β signalling is also linked to adiposity through the regulation of adipocyte differentiation and oxidative metabolism, and TGFB1 is overexpressed in obesity." (PMID 40175777, 2025). "Recent findings have highlighted the importance of specific molecular pathways, notably transforming growth factor beta 1 (TGF-β1), which predominantly enhances the production of type I collagen, in the complex landscape of atrial structural remodeling associated with obesity." (PMID 38396862, 2024).